SPINK1 (serine peptidase inhibitor Kazal type 1)
Diseases named in the same sentence as SPINK1 in open-access papers (continued):
Sharing a sentence is not in itself a finding about the gene and the disease.
ovarian carcinoma (continued). "Beyond its potential use as a prognostic marker, our findings implicating SPINK1 as a functional driver of ovarian cancer cell growth and survival suggest that it may offer a target for pharmacological intervention in the subset of patients with SPINK1-expressing tumors." (PMID 26437224, 2015). "We show that SPINK1 drives ovarian cancer cell proliferation through activation of epidermal growth factor receptor (EGFR) signaling, and that SPINK1 promotes resistance to anoikis through a distinct mechanism involving protease inhibition." (PMID 26437224, 2015). "Serine protease inhibitor Kazal type 1 (SPINK1), a member of the Kazal-type serine protease inhibitor family, was initially identified in the urine of ovarian cancer patients, it is secreted by pancreatic acinar cells into the pancreatic duct, where it inhibits trypsin activity." (PMID 40904507, 2025). "From the resulting candidates, already known ovarian cancer biomarkers were ruled out (e.g. SPINK1/TATI), after which a more detailed analysis of the in silico expression data as well as relevant literature was conducted." (PMID 26981633, 2016). "By contrast, among patients with nonserous epithelial ovarian cancers, those with SPINK1-positive tumors showed significantly poorer survival than those with SPINK1-negative tumors (p = 0.0113)." (PMID 26437224, 2015). "This identifies SPINK1 as an independent prognostic factor in nonserous ovarian cancers, and suggests that SPINK1 expression may precede tumor progression and identify a subset of early stage cancers with poor prognosis." (PMID 26437224, 2015). "Furthermore, treatment of ovarian cancer cells with erlotinib, a selective inhibitor of the EGFR kinase domain, completely blocked the proliferative response of the cells to SPINK1, demonstrating that EGFR signaling is required for SPINK1-stimulated proliferation." (PMID 30778387, 2019). "In addition, our work suggests that SPINK1 may have clinical relevance as a biomarker particularly in currently understudied nonserous ovarian cancer subtypes." (PMID 26437224, 2015). "SPINK1 has been reported previously to stimulate proliferation through activation of EGFR signaling as a putative novel EGFR ligand in several other tumor types, but this phenomenon has not been examined in ovarian cancer models." (PMID 26437224, 2015).
colon cancer (11 papers, 2015 to 2025). "In our previous investigation, the prognostic role of SPINK1 in general colon cancer was studied in vivo, revealing that high SPINK1 expression was associated with advanced cancer stage and poor prognosis." (PMID 36053457, 2022). "In contrast, a high SPINK1 expression level was associated with favorable overall survival in a Kaplan–Meier analysis of stage IV colon cancer patients receiving cetuximab-based targeted therapy." (PMID 33916984, 2021). "In the context of SPINK1, our data favored Kon M’s report in which it was described that the chaperone-mediated autophagy was required for colon tumor growth, showing a new signaling route of SPINK1 that promoted colon cancer growth via reinforced autophagy." (PMID 37305325, 2022). "Among human breast and colon cancers, SPINK1 is considered to be a transforming factor involved in the invasion and metastasis potential of cancer cells, and SPINK1 contained in human colostrum has been shown to promote the proliferation and migration of HT29 cells." (PMID 35194087, 2022). "The clonogenic assay was performed showing that silencing SPINK1 could radio-sensitize colon cancer cell lines, and the combination of si-SPINK1 and radiation was superior to treatment by radiation alone (p < 0.001)." (PMID 36053457, 2022). "Moreover, serum SPINK1 levels are closely related to tumor prognoses such as for ovarian, breast, bladder, and colon cancers, and SPINK1 overexpression serves as a marker of poor tumor prognosis." (PMID 31240230, 2019). "SPINK1 is overexpressed in various solid tumors, such as gastric, breast, and colon cancers." (PMID 31240230, 2019). "Collectively these results suggest that SPINK1 silencing (potentially involving MTs overexpression) confers sensitivity to doxorubicin in colon cancer cells, which strengthen the rationale for using the combinatorial treatment approach for the SPINK1+ CRC patients." (PMID 26258891, 2015). "Further, we sought to determine whether blocking PI3K/AKT and MEK/ERK signaling in SPINK1+ colon cancer cells could hamper SPINK1-mediated oncogenic effects." (PMID 26258891, 2015). "Moreover, we also found that SPINK1-silenced colon cancer cells perform better to doxorubicin treatment in the cell proliferation and invasion assay." (PMID 26258891, 2015). "Notably, SPINK1 and CXCL11 gene copy numbers exhibited a positive correlation with gene mRNA levels, while MAFB copy number displayed a negative correlation with its gene mRNA level in colon cancer tissues." (PMID 38577604, 2024).
diabetes mellitus (11 papers, 2003 to 2023). A metabolic disorder characterized by abnormally high blood sugar levels due to diminished production of insulin or insulin resistance/desensitization. "Seven cases (58.3%) had major pathologies (such as diabetes mellitus, small-cell left lung carcinoma, serine protease inhibitor Kazal type I (SPINK1) gene mutation, and acute alcoholic pancreatitis)." (PMID 37764707, 2023). "According to Sun examining the Chinese population, patients with the c 194+2T>C SPINK1 mutation were diagnosed with the disease at younger age and developed diabetes earlier." (PMID 25838820, 2015). "Though the role of SPINK1 signaling in the retina is yet unknown, a recent study demonstrated a higher incidence of DR in individuals with fibrocalculous pancreatic diabetes, a form of diabetes mellitus often associated with SPINK1 mutations, relative to individuals with type 2 diabetes mellitus." (PMID 34861815, 2021). "The cumulative rates of pancreatic exocrine insufficiency and diabetes mellitus in both patients with PRSS1 and SPINK1 mutations were 16.1% and 5.5% at 20 years of age, and 45.3% and 28.2% at 40 years of age, respectively." (PMID 33375361, 2020). "Our data also suggests that co-existence of TCF7L2 variants and the SPINK1 and CTSB mutations, that predict susceptibility to exocrine damage, may interact to determine the onset of diabetes in TCP patients." (PMID 18706099, 2008).
breast carcinoma (10 papers, 2010 to 2024). "In breast cancer, SPINK1 staining was reported to be widespread in breast tumors, with high SPINK1 associated with poor distant metastasis free survival specifically in estrogen receptor positive (ER+) breast cancer patients." (PMID 26437224, 2015). "SPINK1 expression was linked to poorer outcome and SPINK1 has been shown, when overexpressed in colorectal and breast cancer cells, to function as an autocrine growth factor that can stimulate the PI3K pathway." (PMID 20104229, 2010). "Previous studies in prostate and breast cancers have also demonstrated the efficacy of a monoclonal SPINK1 neutralizing antibody to decrease tumor growth as well as metastatic abilities." (PMID 38030644, 2023). "It has been repeatedly reported that SPINK1 is overexpressed in various types of cancer tissues, such as gastrointestinal, genitourinary, gynecologic, liver, lung, and breast cancers." (PMID 34747365, 2021). "Studies in prostate, colon, pancreatic, and breast cancer models have provided evidence that SPINK1 can promote cancer growth and progression." (PMID 26437224, 2015). "For example, we recently identified serine protease inhibitor Kazal-type 1 (SPINK1) as an important therapeutic target in breast cancer by using a combined genotype and phenotype screening approach." (PMID 22621393, 2012). "Notably, SPINK1 was found to have the most significant impact on the DFS of breast cancer patients with EGFR gain." (PMID 38892065, 2024). "Curry and colleagues showed that treatment of the breast cancer cell line MDA-MB-231 with HKMTI-1–005 induced transcription of SPINK1, which did not occur when EZH2 or G9A were individually knocked down." (PMID 35131874, 2022).
liver cancer (10 papers, 2013 to 2025). An epithelial or non-epithelial malignant neoplasm that arises from the liver. "SPINK1 has been detected in multiple types of cancers including bladder, renal, prostate, and liver cancers." (PMID 35219893, 2022). "Serine protease inhibitor Kazal type 1 (SPINK1) is an acute-phase response protein that is overexpressed in liver cancer tissue." (PMID 31240230, 2019). "Notably, chemotherapy treatment alone enriches CD133+ liver cancer stem cells and increases SPINK1 expression, suggesting why some HCC patients exhibit resistance to chemotherapy." (PMID 38030644, 2023). "The study further indicated that SPINK1 expression may be due to ER stress-induced SPINK1 demethylation during liver cancer progression." (PMID 33916984, 2021). "Therefore, HBV is likely to upregulate SPINK1 expression through its X gene to promote the development of liver cancer." (PMID 31240230, 2019). "Functional studies in breast, prostate and liver cancer cell lines have suggested SPINK1 might inhibit apoptosis." (PMID 23527199, 2013). "The analysis of TCGA liver cancer data showed that the expressions of AGFG1, IQGAP3, SPINK1, CXCL9, MYO1E, and POF1B were significantly increased in tumor tissues." (PMID 41578779, 2025). "We also identified a proliferative cluster, which mainly consisted of proliferating T cells and a large cluster of HCC cancer cells (40%) expressing both genes associated with normal liver function (ALB, HP, FGA, FGB) and liver cancer (AFP, SPINK1, GPC3, AKR1C1)." (PMID 38030622, 2023).
non-small cell lung carcinoma (6 papers, 2021 to 2025). A group of at least three distinct histological types of lung cancer, including non-small cell squamous cell carcinoma, adenocarcinoma, and large cell carcinoma. "In non-small cell lung cancer, inhibition of SPINK1 was found to increase reactive oxidative species production and tumor cell apoptosis mediated by the p38 MAPK signaling pathway." (PMID 36053457, 2022). "SPINK1 is also a prognostic marker for non-small cell lung cancer and a novel antioxidant promoter during oxidative stress in non-small cell lung cancer." (PMID 35252264, 2022). "SPINK1 was highly expressed in non-small cell lung cancer compared with adjacent normal tissue samples." (PMID 33916984, 2021). "SPINK1 is involved in redox homeostasis by activating Nrf2 in non-small cell lung cancer." (PMID 39952200, 2025). "In non-small cell lung cancer, another subtype of lung cancer, functional analyses indicated that SPINK1 induced tumor cell growth and inhibited apoptosis by maintaining redox homeostasis driven by regulating the nuclear factor erythroid 2-related factor two pathways." (PMID 33916984, 2021).
lung carcinoma (5 papers, 2013 to 2023). "Anti-apoptotic effect of SPINK1 was observed in breast and lung cancers, as a caspase independent innate apoptotic pathway." (PMID 36053457, 2022). "The PC9 and H1299 lung cancer cell lines exhibited increased matrix metalloproteinase 12-based migration and invasion after ectopic SPINK1 overexpression, whereas the knockdown of SPINK1 inhibited biological functions." (PMID 33916984, 2021). "A similar result was verified in a cell line panel study showing relatively high SPINK1 protein and RNA expression levels in the H460, H1299 and A549 lung cancer cell lines compared with those in normal human bronchial epithelial (HBE) cells." (PMID 33916984, 2021). "It has been determined that SPINK1 functions as a prognostic marker for lung cancer." (PMID 38093163, 2023). "SPINK1 or tumor-associated trypsin inhibitor (TATI) did not appear to be a good tumor marker in lung cancer, since its sensitivity was poor and the correlation between TATI serum levels and stage of the disease and histological type was weak." (PMID 24299561, 2013).
pancreatic adenocarcinoma (5 papers, 2011 to 2021). "A study using two pancreatic adenocarcinoma cell lines, PaCa44 and PancTu-I, harboring the heterozygous N34S variant further showed reduced SPINK1 levels compared with wild-type SPINK1." (PMID 33916984, 2021). "At the level of germline variants, our results highlight a potential role for trypsinogen-regulating genes, including PRSS1 and SPINK1, in predisposition toward BTC, though the significantly increased risk for pancreatic adenocarcinoma associated with these two genes remains controversial 43,44." (PMID 33754015, 2021). "TATI/SPINK1 is expressed together with EGFR in pancreatic adenocarcinomas." (PMID 24204699, 2013).
bladder cancer (4 papers, 2013 to 2024). "Moreover, elevated serum and urine concentrations of SPINK1 are associated with adverse prognosis in ovarian, kidney, colorectal and bladder cancer." (PMID 24865347, 2014).
Cirrhosis (4 papers, 2013 to 2024). A chronic disorder of the liver in which liver tissue becomes scarred and is partially replaced by regenerative nodules and fibrotic tissue resulting in loss of liver function. "Our study mostly included HCV-induced cirrhotic patients followed by HCV-induced cirrhosis patients but generating similar results with increased SPINK1 transcript correlating HCV-mediated cirrhosis and the risk of its progression to HCC." (PMID 34469466, 2021). "A combination of CTNNB1, SERPIND1 and SPINK1 would generate an AUC of 1 which would be the ideal scenario for early-stage HCC detection when developing from cirrhosis." (PMID 34469466, 2021). "In addition, the SPINK1 protein is overexpressed in HCC which develops in patients with hemochromatosis, and it is shown that SPINK1 gene expression increases during the cirrhosis to HCC transition." (PMID 39272711, 2024). "Theoretically, higher levels of IL6 in chronic hepatitis and cirrhosis might promote HCC through increasing SPINK1." (PMID 23527199, 2013). "ROC curve analysis of these biomarkers showed promising diagnostic value but CTNNB1, SERPIND1 and SPINK1, with AUC as 0.94, 0.88 and 0.89, respectively, demonstrated that they have highest diagnostic ability to detect early stage HCC developing on the background of cirrhosis." (PMID 34469466, 2021). "Our suggested mRNA signature including CTNNB1, RhoA, SPINK1, IFITM3 and SERPIND1, alongside other platelets mRNA, can be utilized as biomarkers for comparison of hepatic cirrhosis and HCC." (PMID 34469466, 2021). "RhoA, CTNNB1 and SPINK1 showed a significant 3.3-, 3.2- and 3.18-folds upregulation, respectively, in HCC patients compared to cirrhosis patients while IFITM3 and SERPIND1 presented a 2.24-fold change." (PMID 34469466, 2021). "However, we did not detect hepatocyte SPINK1 protein expression in the vast majority of cirrhosis samples in this study, suggesting that other factors are also needed to allow SPINK1 expression in HCC cells." (PMID 23527199, 2013). "Therefore, there are no published data on serum SPINK1 comparing HCC and cirrhosis patients." (PMID 23527199, 2013).
exocrine pancreatic insufficiency (4 papers, 2020 to 2025). Inability of the exocrine pancreas to produce and secrete an adequate amount of digestive enzymes into the small intestine. "SPINK1-related SIIEPI also warrants comparison with other genetic forms of early-onset exocrine pancreatic insufficiency, particularly those caused by pathogenic or predisposing variants in CFTR and CEL." (PMID 41009946, 2025). "Exome reanalysis ordered after her later diagnosis of pancreatic insufficiency and chronic kidney disease identified a risk allele in SPINK1, providing an explanation for her pancreatic insufficiency." (PMID 35937981, 2022). "While simple heterozygous LoF SPINK1 variants are well recognized to predispose to or cause CP, biallelic variants resulting in complete LoF of SPINK1 lead to a severe pediatric disorder termed severe infantile isolated exocrine pancreatic insufficiency (SIIEPI)." (PMID 41009946, 2025).
alcohol abuse (3 papers, 2015 to 2025). The use of alcoholic beverages to excess, either on individual occasions ("binge drinking") or as a regular practice. "Furthermore, genetic testing for SPINK1 and CFTR variants—identified in 22% of idiopathic RAP cases—may help identify high-risk individuals even in the absence of alcohol abuse." (PMID 41227226, 2025).
chronic hepatitis (3 papers, 2013 to 2022). An active inflammatory process affecting the liver for more than six months. "The serum SPINK1 levels of patients with LC or HCC were markedly higher than those of patients with chronic hepatitis." (PMID 31240230, 2019).
gastric cancer (3 papers, 2013 to 2025). A primary or metastatic malignant neoplasm involving the stomach. "Although the role of SPINK1 in gastric cancer remains largely unexplored, elevated serum SPINK1 levels have been linked to advanced‐stage gastric cancer." (PMID 40576306, 2025). "SRB analysis, which measures cell viability, revealed that overexpression of SPINK1 increased gastric cancer cell growth." (PMID 40576306, 2025). "In this study, we have uncovered a novel mechanism by which VHL decreases SYT11 protein stability, thereby downregulating SPINK1 expression and inhibiting the growth and invasion of gastric cancer cells." (PMID 40576306, 2025). "To investigate the role of SPINK1 in gastric cancer cells, we assessed gastric cancer cell growth following SPINK1 overexpression." (PMID 40576306, 2025). "Furthermore, SPINK1 knockdown inhibited the growth and invasion of gastric cancer cells, mirroring VHL overexpression effects." (PMID 40576306, 2025). "Similarly, the reduction in gastric cancer cell invasion caused by VHL was restored by the overexpression of SYT11 and SPINK1." (PMID 40576306, 2025). "Finally, we evaluated the role of SYT11 and SPINK1 in VHL‐mediated inhibition of gastric cancer cell growth." (PMID 40576306, 2025). "The VHL‐induced reduction in gastric cancer cell growth and invasion was rescued by overexpression of SYT11 and SPINK1." (PMID 40576306, 2025). "The present study demonstrates that VHL inhibits gastric cancer cell proliferation and invasion by promoting proteasome‐dependent degradation of SYT11, thereby downregulating SPINK1." (PMID 40576306, 2025). "Analyses of public data confirmed that high SPINK1 expression is negatively correlated with post‐progression survival of gastric cancer patients, although it is not significantly correlated with overall survival." (PMID 40576306, 2025). "Moreover, inhibition of SPINK1 suppressed the growth and invasion of MKN1 and SNU484, gastric cancer cells." (PMID 40576306, 2025).
ovarian tumor (3 papers, 2001 to 2017). "The natural physiological targets of SPINK1 in the pancreas are trypsin 1 (cationic trypsin) and trypsin 2 (anionic trypsin); both of these enzymes can be expressed by ovarian tumors, and in this context are known as tumor-associated trypsin 1 and 2, respectively." (PMID 26437224, 2015).
prostate adenocarcinoma (3 papers, 2020 to 2023). "This study aimed to investigate the relationship between renal function parameters and distinctive molecular subtypes of prostate adenocarcinomas, defined by the immunoexpression of the SPINK1, ERG, HOXB13, and TFF3 markers." (PMID 37894380, 2023). "Here, we confirm these findings that Spink1 and Spink5, serine protease inhibitors of Kazal-type, are downregulated by miR-32 both in normal prostate and prostate adenocarcinoma." (PMID 35228520, 2022). "Notably, similar to our SPINK1 and AR IHC data in prostate adenocarcinoma patients, WCM12 also showed positive staining for SPINK1 and was negative for AR expression." (PMID 31959826, 2020).